LRP2 (LDL receptor related protein 2)
Diseases named in the same sentence as LRP2 in open-access papers (continued):
Sharing a sentence is not in itself a finding about the gene and the disease.
tumor (25 papers, 2018 to 2026). "Overall, these findings position LRP2 mutations as valuable tools for personalizing EC immunotherapy, emphasizing the need to consider both genetic and immunological dimensions of tumor behavior." (PMID 41181115, 2025). "Understanding LRP2 mutations’ context—their role as both passenger events and modifiers of tumor behavior, alongside other genetic alterations and the tumor’s immune landscape—provides insights for personalized treatment." (PMID 41181115, 2025). "Tumour antigens LRP2 and DOCK8, which are associated with prognosis and tumour-infiltrating antigen-presenting cells, were identified in KIRC." (PMID 36851274, 2023). "We then found that LRP2 mutations in EC were most strongly associated with immune cells, immune checkpoints and inflammation-related molecules compared to other tumor types." (PMID 35834061, 2022). "Like patient 16, two private mutations in each tumour sample of patient 57 impacted the same gene; however, in patient 57, that gene is LRP2." (PMID 33946379, 2021). "Mutations in LRP2 can be used as a biomarker for personalized tumor immunotherapy." (PMID 36253874, 2022). "Then, we compared the impact of LRP2 mutations on prognosis in different tumor types." (PMID 35834061, 2022). "Importantly, in specific tumor types, LRP2 mutations were associated with MHC molecules, immune receptors, immunostimulators and chemokines." (PMID 35834061, 2022). "We did not perform in vitro or in vivo manipulations (overexpression, knockdown, or knockout) of LRP2, CUBN, CAV1, GIPC1, or DAB2IP to establish causality between expression changes and tumor phenotypes." (PMID 41374987, 2025). "Because subtype-resolved ocular data for LRP2 remain sparse, related evidence from development and other tumor types helps contextualize our results." (PMID 41374987, 2025). "Specifically, LRP2 expression in RCC has been associated with a high tumor mutation burden and with the abundance of tumor-infiltrating immune cells (PMID 36851274)." (PMID 40373089, 2025). "Patients with LDL-receptor-related protein 2 (LRP2) overexpression in tumour tissues had significantly longer survival than patients with low LRP2 expression." (PMID 36851274, 2023). "These examples provide evidence that LRP2 silencing is related to a dedifferentiated tumor state in various epithelial cancer types." (PMID 36980716, 2023). "Conversely, hypermethylation of the LRP2 gene identified relatively good prognosis stage II CC tumours characterised by intact DNA repair pathways and active anti-tumour immunity." (PMID 36612154, 2022). "The important value of LRP2 mutation was easily understand because LRP2-mutated tumor had high levels of TMB, MSI, tumor-infiltrating lymphocytes and immune checkpoint genes expression." (PMID 35834061, 2022). "explained that LRP2 played an important role in tumor cell motility and the tumor metastasis mechanism regulated by Hsp90α51." (PMID 33432021, 2021). "Dysregulated lipid metabolism has been implicated in tumor progression, yet the function of low-density lipoprotein receptor-related protein 2 (LRP2) in CRLM and oxaliplatin (Oxa) resistance has not been defined." (PMID 42215454, 2026). "Across tumor subtypes, LRP2 expression was consistently diminished." (PMID 41374987, 2025). "Interestingly, MC5 (PIK3R1, ITPR2, LRP2) was mainly seen in pre-treatment tumor cells of positive immune state change group." (PMID 38714665, 2024). "LRP2 expression in bulk RNA sequencing samples could potentially be derived from multiple cell types in the tumor microenvironment." (PMID 36980716, 2023). "More complex mechanisms are also possible, where LRP2-mediated clearance of certain molecules from the tumor microenvironment could modulate functions of immune or stromal cells." (PMID 36980716, 2023). "LRP2 was detectable, although to a varying degree, across all 12 tumor samples." (PMID 36980716, 2023).
tumor (continued). "Importantly, we collected 19 KIRC samples and verified the high expression of DOCK8 and LRP2 in tumour tissues, confirming the feasibility of their development as mRNA vaccines." (PMID 36851274, 2023). "Therefore, LRP2 levels in tumor bulk RNA measurements can be considered to reflect tumor-specific expression and to correlate with protein abundance." (PMID 36980716, 2023). "Thus, LRP2 levels measured in tumor bulk RNA sequencing data reflect tumor-specific expression and correlate with protein abundance." (PMID 36980716, 2023). "In addition, we performed the expression profiles of significantly mutated genes in one normal group and two tumor groups; we identified 20 DEGs; among them CSMD3, DCHS2, LRP2, RYR2, and ZFHX4 were significantly negatively correlated with PFS." (PMID 35975176, 2022). "In addition, we performed the expression profiles of significantly mutated genes between the normal group and tumor groups and identified 20 differentially expressed genes (DEGs); among them, CSMD3, DCHS2, LRP2, RYR2, and ZFHX4 were significantly negatively correlated with PFS." (PMID 35975176, 2022). "Specifically, MYOC, TBK1, COL1A1, and COL1A2 were upregulated in tumor tissues, while FOXC1, LRP2, and TEK was downregulated (all p < 0.05)." (PMID 40808675, 2025). "Specifically, LRP2 was significantly downregulated in RB compared to controls, whereas CUBN, DAB2IP, GIPC1, and CAV1 were significantly upregulated in tumor tissue." (PMID 41374987, 2025). "We found that the expression of 9 DE-ceRNAs were significantly different between tumor tissues and normal tissues, including the upregulated H19, HOTAIR, miR222, miR148a, PCDHGB4, GMNC and HMGA2 and the downregulated LRP2 and MBP in tumors." (PMID 40351420, 2025). "Of note, we further detected the gene expression levels of tumour antigens in tumour and normal tissues of 19 KIRC patients and found that the expression levels of DOCK8 and LRP2 in tumour tissues were significantly higher than normal tissues." (PMID 36851274, 2023). "Based on a comprehensive analysis of the immune characteristics and prognosis of KIRC cells, LRP2 and DOCK8 are potential tumour antigens for mRNA vaccine development and are suitable for IS1–4 patients." (PMID 36851274, 2023). "Herein, we found that 5 genes (Shisa3, PADI1, LRP2, ANGPTL4 and ALOX15B) were upregulated and 4 genes (CXCL9, ADAMDEC1, SCGB1A1/CC10, HLA-G) were downregulated in PR tumor tissues compared to SD tumor tissues." (PMID 31801598, 2019). "We expected that the four genes (SACS, LRP2, WDR87, and XIRP2) that were detected in all POLE category tumours with POLE p.P286R or p.V411L would exhibit high PS if this score reflected an accumulation of biased mutation patterns." (PMID 29880869, 2018). "Furthermore, LRP2, NAT8 and ACE2, have been shown to modulate the tumor microenvironment of RCC, a critical factor influencing the response of antiangiogenic drugs and immunotherapy." (PMID 40373089, 2025). "In addition, the expression levels of LRP2 and DOCK8 were positively correlated with the abundance of tumour-infiltrating immune cells, including B cells, macrophages, and DCs." (PMID 36851274, 2023). "This showed that the negative correlation is strongest in tumor types that on average express the highest levels of LRP2 (KIRC, KIRP, MESO, THCA and BRCA)." (PMID 36980716, 2023). "By the same approach, ‘TGFβ-dominant’ (C6) and ‘lymphocyte depletion’(C4) immune subtypes were absent from the LRP2 ‘high’ versus ‘low’ methylation tumour groups." (PMID 36612154, 2022).
tumor (continued). "Interestingly, our analyses also demonstrate that the prognostic value of LRP2 appears to be independent of clinicopathologic variables, such as age, gender, tumor stage, and histological grade." (PMID 36980716, 2023).
infection (4 papers, 2017 to 2024). The state of being infected such as from the introduction of a foreign agent such as serum, vaccine, antigenic substance or organism. "We observed that genes involved in cholesterol uptake (Lrp2) (denoted in grey across the figures) and biosynthesis (Aacs, Hmgcs1, Mvd, Dhcr24) were significantly upregulated during infection; while those implicated in efflux (Abca1, Abcg1) showed a marked downregulation." (PMID 37871034, 2023). "For example, insect defensin promotes the adsorption and infection of Japanese encephalitis virus through LRP2, suggesting a potential role for LRP2 in host–pathogen interactions." (PMID 39311763, 2024).
kidney (2 papers, 2024 to 2025). "Lrp2 KO mice had significantly increased transcript levels of acute kidney injury markers, kidney injury molecule-1 (KIM-1; Havcr1), and neutrophil gelatinase-associated lipocalin (NGAL; Lcn2), compared with control mice." (PMID 38984983, 2024). "Surprisingly, despite their lower weight gain and fat accumulation, male Lrp2 KO mice on WD developed significant kidney injury." (PMID 38984983, 2024).
heart disease (1 paper, 2020). "As an example of our heart disease gene discovery platform, we identified LRP2 as a novel candidate CHD gene with rare variants that are enriched in HLHS patients, thus generating hypotheses for further studies." (PMID 33006316, 2020).
neuromuscular disease (1 paper, 2018). "Only two novel heterozygous missense mutations were identified in the LRP2 (low density lipoprotein-related protein 2) and GXYLT1 (glucoside xylosyltransferase 1) genes, which have no known roles in neuromuscular disease." (PMID 29879922, 2018).
LRP2 also shares sentences with these, for which no sentence is quoted: lung squamous cell carcinoma (3 papers); Cognitive impairment (2); coloboma (2); colon adenocarcinoma (2); Dent-2 disease (2); diabetic nephropathy (2); dyslipidemia (2); hypoplastic left heart syndrome (2); mesothelioma (2); papillary thyroid carcinoma (2); renal fibrosis (2); acute kidney injury (1); adenoma (1); amyloid (1); angiosarcoma (1); Ataxia (1); atrial septal defect (1); bone disorder (1); brain tumors (1); cardiovascular diseases (1); Central hypothyroidism (1); central obesity (1); Cerebral ischemia (1); chordoma (1); cognitive decline (1); diaphragmatic hernia (1); endothelial dysfunction (1); epilepsy (1); epithelioid mesotheliomas (1); esophagogastric adenocarcinoma (1).
A further 49 diseases each share a sentence with LRP2 in 1 paper.